IL1B (interleukin 1 beta)
Diseases named in the same sentence as IL1B in open-access papers (continued):
Sharing a sentence is not in itself a finding about the gene and the disease.
infection (continued). "We observed that the infection induced upregulation in the mRNA expression of liver IL-1β, IL-6, IFN-γ, and TNF-α, while treatment of P. chabaudi-infected mice with IE resulted in a significant downregulation in the expression levels of these cytokines." (PMID 30838089, 2019). "In a parallel experiment, the peritoneal bacterial burden and IL-1β levels in the serum were evaluated at 8 h post infection." (PMID 30761140, 2019). "Using a murine infection model, IL-1β signaling was shown to be a critical step in promoting a protective Th17 response during B. pertussis infection and to be essential in the clearance of B. pertussis." (PMID 31507615, 2019). "IL-1β is a major proinflammatory cytokine that in many infections is instrumental in coordinating the immune response." (PMID 30552162, 2019). "The level of IL-1β mRNA and IL-1β protein in BMDMs of C57BL/6 mice was increased after DENV2(NGC) infection." (PMID 31824450, 2019). "Many previous studies have shown the important role of hemolysin and CNF in IL-1β secretion by macrophages upon infection via pathways that include activation of Rho GTPase, NF-κB, inflammasomes, and pyroptosis." (PMID 31666593, 2019). "In fish, many studies have indicated that regulation in T cells and B cells were mediated by cytokines such as TNF-α and IL-1β, or infection by pathogens." (PMID 31798571, 2019). "In contrast, under the influence of the pro-inflammatory cytokine IL-1β the peak radiance at the height of infection was strongly increased, even exceeding the upper limit of detection over a large area of the skin." (PMID 31156635, 2019). "Recently study by Rogo and colleagues reported the effects of defined SNPs in IL-1β, IL-10, IL-17, and IL-28 in flu A/H3N2 in Iranian population that showed a higher risk of developing a severe infection." (PMID 31196204, 2019). "IL-1β is also a potent pro-inflammatory cytokine that plays an important role in host-defense responses to infection injury, and this protein is expressed in many cells including macrophages." (PMID 31547823, 2019). "TNF-α, IL-1β, and IL-6, 3 important pro-inflammatory cytokines, are widely accepted as downstream factors subsequent to pathogen infection and demonstrated a similar pattern." (PMID 31447841, 2019). "The pro-inflammatory cytokines interleukin (IL)-1β and IL-6 levels in mouse blood plasma were significantly elevated upon infection of the wild type (PBS + DMSO vs. WT + DMSO)." (PMID 30867441, 2019). "The importance of inflammasomes and IL‐1β in particular in protecting against infection has been primarily studied in the context of bacterial infections." (PMID 31468569, 2019). "The hDPP4-Tg mice infected with MERS-CoV overexpressed caspase-1 in the spleen and showed high IL-1β levels in serum, suggesting that pyroptosis occurred after infection." (PMID 30634407, 2019). "In cardiac cultures infected with T. cruzi, different cytokines and chemokines such as TNF-α, IL-1β, and iNOS are secreted in response of the infection." (PMID 31569452, 2019). "IL-1β is a potent pro-inflammatory cytokine that is induced by infection and injury and coordinates both the innate and adaptive immune responses." (PMID 31449558, 2019). "In the Hp infection study, both YAP1 and IL‐1β expression showed an infection time‐dependent trend, which provided a clue into the novel mechanism." (PMID 31145543, 2019). "By contrast, IL-1β levels in HMPV-infected mice were significantly decreased upon MCC950 treatment on day 1 post-infection." (PMID 30964929, 2019). "The cytokine profiles of the brain from TLR9-deficient mice after EV-A71 infection exhibit decreased type-I IFN production but the increased production of several cytokines, including IFN-γ, IL-6, IL-1β, MIP-1α, MCP-1 and IP-10." (PMID 31787104, 2019). "Directing secreted IL-1β into the uterine lumen ensures that the cytokine is localized to the primary site of infection, ready to activate neutrophils recruited to the lumen." (PMID 30804935, 2019).
infection (continued). "By using western blot we found that NLRP3 was required for CASP1 (p20) and IL-1β (p17) cleavage in response to infection." (PMID 31479495, 2019). "Atg16l1fl/flLysmCre mice had significantly more IL-1β in BALF 1 day after infection compared with control animals, corroborating out in vitro data." (PMID 31031755, 2019). "During the first days of the infection significantly increased numbers of neutrophils (CD11b+Ly6G+ cells) were also found in the blood of mice implanted with IL-1β filled pumps while the effect of other cytokines on neutrophil counts were minimal." (PMID 31156635, 2019). "We previously showed that IL-1β production via the NLRP3 inflammasome is critically required to control CP growth to successfully resolve the infection in mice." (PMID 31031755, 2019). "Although the H5N1 NP inhibited TNF-mediated NF-κB activation and the H5N1 NA activated NF-κB downstream of IL-1β in this paper, it has been reported that the overall NF-κB activation status upon infection by the H5N1 subtype is activated." (PMID 31772934, 2019). "We found that infection with L.g.− induced a more robust IL-1β production when compared with L.g.+, an effect observed as early as 9 h after infection." (PMID 31754185, 2019). "We also found a clear increase in inflammation in the lungs 6 days after infection, correlating with the increase in neutrophils and IL-1β in the BALF, as well as the greater bacterial burden." (PMID 31031755, 2019). "YAP1 transcriptionally activates IL‐1β in GC cells, which is beyond the classic mechanism involving immune cell responses, and creates a complete inflammatory environment wherein the infection occurs." (PMID 31145543, 2019). "Over a period of 1 – 5 days, we found that IL-1β secretion increased steadily over time, peaking at 4 days post-infection." (PMID 30956972, 2019). "The induction of TNF-α, IL-6, and IL-1β was maintained at relatively low levels compared with infection with L. monocytogenes or treatment with LPS." (PMID 31877174, 2019). "Our data demonstrate that mice infected with the ΔmsbA strain showed a reduction of important inflammatory mediators like TNF-α and IL-1β, resulting in almost a 30% reduction of both cytokines, after 24 h of infection." (PMID 31217305, 2019). "In other models of inflammation and infection, inflammatory cytokines such as IL-1β, TNF, IL-6 and IFN-γ are thought to be the major mediators of DME down-regulation." (PMID 31299982, 2019). "Consistently, E. faecalis pretreatment also suppressed the IL-1β secondsretion induced by fecal content treatment or infection with E. coli or P. mirabilis." (PMID 30823406, 2019). "In the early stage of infection (6 hpi), pro-inflammatory cytokines (IL1β, IL8) and LSZ were significantly up-regulated in the immune organ of grass carp fed with SL001-diets, which was beneficial to the body against pathogens." (PMID 31316478, 2019). "The strain employed in this study (PAO1) lacks the exoU gene, which would account for the relatively low levels of IL-1α detected in the infection assays, particularly in comparison with IL-1β." (PMID 30455194, 2019). "PMNs were the primary source of IL-1β in vivo during this infection, and IL-1β cleavage during infection was dependent on neutrophil elastase, which is a serine protease." (PMID 31703354, 2019). "IL1β and the IFNγ-inducing factor IL18 released by canonical inflammasomes are inflammatory and host protective, as IL1β recruits neutrophils to sites of infection and IFNγ activates phagocyte microbicidal activities." (PMID 30728749, 2019). "Tc infection increased plasma levels of IL-1β as well as other HPA axis-activating cytokines such as TNF-α, IFN-γ, or IL-6." (PMID 31998227, 2019). "IL1B is a major proinflammatory cytokine that is produced by monocytes, macrophages and dendritic cells during infection and inflammation." (PMID 30792445, 2019).
infection (continued). "In a model of P. gingivalis infection in vivo, we showed that the P2X7 receptor was required for IL-1β production, leukocyte recruitment to the site of infection, and bacterial clearance." (PMID 31341421, 2019). "A report emphasized that ARV induced inflammatory response (secretion of IL-1β and IL-6) and delayed apoptosis in the early stage of infection." (PMID 31126305, 2019). "Data from a mouse post-arthroplasty infection model revealed that the recruitment of neutrophils to the site of infection depends on IL-1β." (PMID 31396229, 2019). "While the ancient lineages impair the autophagic flux, infection with the modern strains leads to a stimulation of this process, which is dependent on the increased production of IL1-β triggered by these mycobacteria." (PMID 32038614, 2019). "Meanwhile, upon infection, the expression of IL-1β and TNF were decreased with epinecidin-1 plasmid electroporation, supporting the protective role of Epi-1 against mortality caused by overexpression of immune-related genes." (PMID 31824449, 2019). "IL-1β was reported to be important for the rapid production of anti-bacterial IgM by innate-like B cells important for early containment of infection prior to the induction of adaptive immune responses." (PMID 31700615, 2019). "Interleukin (IL)-1β levels were below the limit of detection for all cynomolgus macaques, whereas levels were detectable in three of the four rhesus macaques prior to infection." (PMID 31831787, 2019). "Infection by DENV2(NGC) resulted in the activation of IL-1β secretion, Casp-1 p20 maturation, IL-1β p17 processing, and DENV2 NS3 production." (PMID 31824450, 2019). "E. faecium upregulated the mRNA expression of PPAR-γ and IL-10 (P < 0.05) and downregulated that of NF-κB, TLR4, and IL-1β (P < 0.05) in the spleen 3 and 7 days post-infection." (PMID 29948799, 2019). "During P. aeruginosa infection, macrophages treated with IFN-γ or IL-17A displayed comparable levels of LDH release and active caspase-1 upon infection with P. aeruginosa, suggesting similar capacities to process pro-IL-1β." (PMID 30455194, 2019). "IL-1β is activated by caspase-1, and is critical for the response to infection as it influences the production of NO." (PMID 31775245, 2019). "First, at 48 h postinfection during the peak of the lung injury, we examined expression of infection-induced production of pro–IL-1β within alveolar Mφs, a precursor for inflammasome activation." (PMID 31586037, 2019). "Similar to the case in cells infected by the WT strain, infection with the Δplc mutant induced caspase-1 activation and cleavage/release of IL-1β." (PMID 31708887, 2019). "Systemic levels of both IL-1α and IL-1β were measured in plasma, liver and spleen following infection with the classical European ST1 strain P1/7 and the highly virulent ST7 strain SC84." (PMID 31262357, 2019). "The inhibitory effect appeared only in the late infection, where levels of pro-IL1β and procaspase-1 mRNA and the mature IL1β protein decreased to mock level." (PMID 30862035, 2019). "Our data suggest that ERS induces macrophages to produce mature IL-1β during infection with virulent M. bovis through a positive feedback loop between mitochondrial damage and inflammasome activation." (PMID 30846986, 2019). "The level of the pro-inflammatory cytokines TNF-α, IL-1β and IL-6 and the anti-inflammatory cytokine IL-10 was quantified at 10 h post-infection in the supernatants of infected MDM." (PMID 31694333, 2019). "IL-1β is produced primarily by activated macrophages and possess multiple and diverse properties in their response to infection." (PMID 30841905, 2019). "Initial studies highlight an upregulation of key ILC2- inducing alarmin genes Il1a, Il1b, Il33, and Tslp shortly (6 h) after percutaneous S. mansoni cercariae infection of the pinna." (PMID 31024526, 2019).
infection (continued). "In line with an increased infection rate, smoking reduced 25OH vitamin D3 (immune-modulatory), IL-1β, IL-6, TNF-α, and IFN-γ serum levels." (PMID 30909629, 2019). "When infection experiments were performed in the presence of Bay compound that inhibits NFκB, the secretion of IL-1β was significantly inhibited." (PMID 32038610, 2019). "Our results revealed that IL-1β mRNA level was higher in the infected cerebral cortex of WT mice on 3 days post-infection as compared with infected TLR7-/- mice." (PMID 31730654, 2019). "The P2X7-dependent IL-1β release observed during nga(G330D) infection is sensitive to several of the ion and ABC channel inhibitors tested." (PMID 31275321, 2019). "S. Typhimurium induced the expression of IL-6, IL-8, IL-1β, TNFα and IL-10 genes in CaCo-2 cells after 8-h infection." (PMID 31490973, 2019). "Particularly, TNF-α and IL-1β are produced in large amounts by polymorphonuclear leukocytes and activated macrophages during the initial stages of infection." (PMID 31847340, 2019). "IL-1β production is caspase mediated during infection of human phagocyte stepwise cocultures with P. aeruginosa." (PMID 30455194, 2019). "A study conducted in a GBS-induced infection in mice demonstrated that 82% and 7% of IL-1β-positive cells were PMNs and macrophages, respectively, suggesting a crucial role of PMNs in the production of IL-1β and thereby amplifying their own recruitment." (PMID 31197179, 2019). "Significantly increased production of TNF-α, IL-6, and IL-1β was detected after infection with the wild-type strain compared to that with the ΔbceR strain." (PMID 30728810, 2019). "il-1β signaling is required for protective NO production by neutrophils and a subsequent decrease in infection." (PMID 30552162, 2019). "The transcription levels of IL-1β (at 12 and 24 h.p.i.)and IL-18 (from 12 to 36 h.p.i.)were significantly (P < 0.05) increased in the vvIBDV infection group compared with the corresponding control groups." (PMID 31632367, 2019). "The mRNA expression level of IL1β can be upgraded by CATHs, which are AMPs that play an important role during infection with the fish pathogen Yersinia ruckeri." (PMID 31921142, 2019). "The abundance of active IL-1β by ELISA in coinfected ears at day 1 and day 3 p.i. compared to all other infection groups." (PMID 31107882, 2019). "IL-1β plays an important role in mediating autoinflammatory diseases and in generating inflammatory responses to infection." (PMID 30634407, 2019). "IL-1β-mediated bacterial killing has been demonstrated in infections of macrophages with other extracellular bacteria, such as Pseudomonas aeruginosa." (PMID 30297526, 2019). "Seemingly contradictory observations have been reported regarding the effects of infection and virion inactivation by UV on IL-1β secretion from monocytes, smooth muscle cells, and endothelial cells." (PMID 30755509, 2019). "Although nearly all the strains induced significant increases in MCP-2 and IL-1β compared to mock infection using ELISAs, these cytokines were more robustly induced by the four ST-17 strains." (PMID 31536604, 2019). "On the contrary, CytoD induced a dose-dependent reduction of IL-2 production by DCs, IL-10 by PMNs and IL-1β by MPs in response to infection by all rBCG strains." (PMID 31921172, 2019). "Our results indicated that the levels of active caspase-1 and mature IL-1β induced by either fecal content treatment or infection with E. coli or P. mirabilis were decreased in THP-1 cells pretreated with E. faecalis compared with untreated cells." (PMID 30823406, 2019). "NDK also decreased ATP-induced IL-1β release and inhibited ATP-induced host cell death after infection with P. gingivalis." (PMID 31341421, 2019). "Blood TNF-α and IL-1β levels and systemic parasite burden were evaluated 5–40 days after the infection." (PMID 31138231, 2019).
infection (continued). "Even though lethal infection induces a marked production of the proinflammatory cytokine IL-1β by monocytes, this is contrasted by the expression of considerable amounts of mRNA for the regulatory cytokine IL-10 by these cells." (PMID 31570561, 2019). "The IL-1β ELISA confirmed robust and significant IL-1β production compared to mock infection for all 15 GBS strains." (PMID 31536604, 2019). "In a similar chronic model of infection by L. borgpetersenii serogroup Ballum, cytokines IL-1β and IL-10 were upregulated in hamster kidneys compared to OF1 mouse strain after 14 and 21-28 days postinfection." (PMID 31687410, 2019). "Inoculation of commensal Lactobacillus plantarum in the intestinal loops led to a rapid anti-inflammatory response and epithelial tight junction repair by dampening SIV-infection-induced NF-κB/IL-1β signaling in gut of early SIV-infected macaques." (PMID 31191468, 2019). "Here we show that although BMDMs infected with S. pneumoniae exhibit large amounts of pro-IL-1β and pro-Caspase-1, accumulation of the processed forms (IL-1β p17 and Casp-1 p20) is highly delayed and remains undetectable until 6 to 12 h post infection." (PMID 31375698, 2019). "We expected that, if true, the addition of this compound during nga(G330D) infections would increase IL-1β secretion even further." (PMID 31275321, 2019). "Infection with this chronic gastrointestinal nematode has been shown to promote the release of host-derived IL-1β, which limits IL-25 production and the subsequent activation of ILC2s." (PMID 31024526, 2019). "Infection of either the PKCδ KO or CARD9 KO THP-1 cells with T. gondii resulted in reduced IL-1β release compared to infection of the EV cells." (PMID 31449558, 2019). "The ability of IL-1β neutralizing antibodies to dramatically reduce lesion formation and significantly lower IL-1β levels when administered subcutaneously at the infection site is encouraging." (PMID 30018884, 2018). "IL-1β has been shown to be protective against infections by upregulating chemotactic chemokines and recruiting neutrophils to inflammatory sites." (PMID 29616195, 2018). "In the liver on day 7 post-infection, the expression of iNOS, IL-1β, IL-6, IL-12 p40, TNF-α, IL-10, TGF-β, CCR2, CCL2, IFN-γ and IL-4 was significantly up-regulated, and the expression of Arg-1 was down-regulated in both of MRP14-KO mice and WT mice." (PMID 29902248, 2018). "Conversely, IL-1β-induced eicosanoids were shown to inhibit the actions of type I IFN during influenza virus or M. tuberculosis infection, with opposite outcomes for disease." (PMID 29559569, 2018). "IL-1β mRNA was still expressed in the lung and spleen (vs. the blank group, P < 0.05) at the endpoint of the study (42 d post-infection)." (PMID 29490620, 2018). "The NLRP3 inflammasome responds to infection and tissue damage, and rapidly escalates the intensity of inflammation by activating interleukin (IL)-1β, IL-18 and cell death by pyroptosis." (PMID 30069026, 2018). "The infection of R848-primed BMDMs with live E. coli resulted in a significantly increased production of IL-1β and TNF-α as compared with unprimed BMDMs." (PMID 29515583, 2018). "Seven to 28 days after infection, significant amounts of IL-1α, IL-1β, MIG, and VEGF were expressed in spleens from BALB/c mice." (PMID 30500862, 2018). "Past research suggests that pro-inflammatory cytokines IL-1β and TNF-α play a primary role in inducing infection-associated PTB." (PMID 29867970, 2018). "At 72 h post-infection, the mice were sacrificed and plasma samples as well as the skin tissue surrounding the infection site were harvested for IL-1β analysis." (PMID 30018884, 2018). "In our previous study, the expression and secretion of IL-1β and IL-6, the major Th17-polarizing cytokines, increased in DCs upon infection with the WT strain." (PMID 30283443, 2018).